CD4 (CD4 molecule)
Diseases named in the same sentence as CD4 in open-access papers (continued):
Sharing a sentence is not in itself a finding about the gene and the disease.
dyslipidemia (100 papers, 2004 to 2026). "Among HIV-infected participants, high viral load was significantly associated with increased risk of dyslipidemia, even after adjusting for age and gender, and lower CD4 cell count was also associated with dyslipidemia." (PMID 28599673, 2017). "While low CD4 count has been associated with increased risk of dyslipidemia in SSA, to date, the association of viral load with dyslipidemia has not been assessed as viral load testing is not routinely conducted in these settings due to limited resources." (PMID 28599673, 2017). "Reasons for RPV/FTC/TDF initiation were simplification (n = 4; 24%); toxicities (neurological, associated with EFV, n = 2, 12%; dyslipidemia, n = 2, 12%); viral failure (n = 8; 47%) and CD4 count below 350/μL in the naïve patient." (PMID 27310962, 2016). "Such association of APOA5 towards dyslipidemia was accompanied by a 21% decrease of the CD4 T-cell count (p=0.024) and a 19% increase in CD8 T-cell count (p=0.002) in carriers of the rare allele in the APOA5 rs662799 polymorphism adjusted by age and gender." (PMID 25394062, 2014). "Univariate models indicated that gender, drinking history, triglyceride levels, high fasting plasma glucose, metabolic syndrome, and CD4 count was associated with liver steatosis." (PMID 23941464, 2013). "Additionally, metabolic stress caused by dyslipidemia has been shown to induce harmful immune activation, resulting in high levels of CD4 + T cells and lowered HBeAg seroconversion, most probably as a consequence of cellular dysfunction." (PMID 34717643, 2021). "Similarly, association between a low CD4 cell count and higher prevalence of dyslipidemia is in keeping with the HIV-induced inflammation mechanism." (PMID 28599673, 2017). "The association between dyslipidemia and CD4 cells count was significant (p = 0.027)." (PMID 29610642, 2017). "Moreover, patients with metabolic syndrome associated lower levels of activated T CD4+ lymphocytes at treatment initiation which could contribute to worse rifaximin response." (PMID 35165326, 2022). "By modeling quantiles for residual lifetimes to the onset of dyslipidemia and applying our proposed induced smoothing method, we dynamically assessed the effect of CD4 cell count, a longitudinal biomarker, for different evaluation times and quantiles." (PMID 38368350, 2024). "The rs1130214 has been associated with persistently high CD4+ T cell glycolytic activity in HIV-positive individuals, increased risk of having congenital heart disease, glucose homeostasis and metabolic syndrome, among other conditions." (PMID 39439795, 2024). "The balance established between Th17 and Treg subpopulations, which represent two distinct CD4+ T cell phenotypes with completely different functions, is crucial for preventing immune imbalance, autoimmune responses, and pathogenesis of the metabolic syndrome." (PMID 39683500, 2024). "The study subjects who fulfilled the inclusion criteria were all male, with a median age of 49 years and a median CD4+ count of 802 cells/μL, and 60% of them had metabolic syndrome." (PMID 39062027, 2024). "Other significant baseline characteristics more frequently seen in participants presenting peripheral neuropathy included larger height (p = 0.048), lower nadir CD4 cell count (p = 0.005), and metabolic syndrome (p = 0.001)." (PMID 38275937, 2023). "Though severe immune suppression (low CD4 count) has been associated with dyslipidemia in HAART-naive HIV patient, in a cohort of persons doing well on HAART with a sufficiently improved mean CD4 count, there is only little variability in the TC of the group." (PMID 35776747, 2022). "We show that, although an increased percentage of circulating CD3+ lymphocytes was detected in metabolic syndrome patients, as previously reported, both CD4+ and CD8+ cells were responsible for this enhancement." (PMID 31109070, 2019).
dyslipidemia (continued). "In short, mTOR activation can determine the metabolic pathway in CD4+T cells of SLE patients to induce metabolic syndrome." (PMID 31395799, 2019). "In summary, our results demonstrate a high prevalence of dyslipidemia characterized by low-HDL and associated with a high viral load and low CD4 cell count." (PMID 28599673, 2017). "Among ART-naïve HIV-infected adults, high viral load and low CD4 cell count were independent predictors of dyslipidemia, underscoring the importance of early initiation of ART for viral suppression." (PMID 28599673, 2017). "Among antiretroviral-naive HIV-infected Chinese adults, there was a high prevalence of dyslipidemia characterized by high TG and low HDL, which was associated with lower CD4 counts." (PMID 26632908, 2015). "In a multivariate analysis using a logistic regression model, we analyzed factors associated with the presence of dyslipidemia among HIV-positive subjects, including sex, age, ethnicity, HIV transmission route, CD4 count, and HCV serostatus." (PMID 26632908, 2015). "In conclusion, among antiretroviral-naive HIV-infected Chinese adults, there was a high prevalence of dyslipidemia characterized by high TG and low HDL, which was associated with lower CD4 counts." (PMID 26632908, 2015). "Notably, PLWH with a baseline CD4+ T-cell count over 500 cells/μl displayed a higher dyslipidemia prevalence compared with those with lower counts (35.5% vs. 23.3%, QB = 8.0, P = 0.02)." (PMID 40585401, 2025). "In addition, GLMM analysis also showed that age, gender, BMI, CD4 count, and ART duration were associated with dyslipidemia." (PMID 37181701, 2023). "The PWH in the SNF-2 (45%) had a severe at-risk metabolic profile with increased visceral adipose tissue, BMI, higher incidence of metabolic syndrome (MetS), and increased di- and triglycerides despite having higher CD4+ T-cell counts than the other two clusters." (PMID 36794912, 2023). "Some studies suggest that dyslipidemia in HIV-infected patients may result in worse CD4 recovery outcomes." (PMID 36298842, 2022). "Therefore, the difference in dyslipidemia of the current patients cannot be attributed to the variations in CD4 count." (PMID 35776747, 2022). "Indeed, some CD8+ cell-derived cytokines, such as TNFα, are significantly elevated in a metabolic syndrome scenario, whereas those that are derived from CD4+ lymphocytes either remained unchanged or decreased (IL-4)." (PMID 31109070, 2019). "Among HIV-infected participants, CD4 cell count was associated with dyslipidemia, with those having a CD4 cell count <350 cells/μl having a 30% higher likelihood of having dyslipidemia compared to those with CD4 cell count >350 cells/μl (PR = 1.31, 95% CI: 1.04, 1.41, p = 0.001)." (PMID 28599673, 2017). "Consistent with previous findings in metabolic syndrome, we found that CD4+iNKT cells can enhance M2 polarization, which may contribute to protection against MSU crystal -induced inflammation." (PMID 29312287, 2017). "In HIV patients, non-traditional cardiovascular risk factors are low CD4 count, lipodystrophy syndrome, C hepatitis co-infection, metabolic syndrome, end-stage renal disease and antiretroviral therapy." (PMID 27015634, 2016). "Additionally, CD4+ T-cell count over 500 cells/μl at baseline was related with higher prevalence of dyslipidemia among PLWH in this meta-analysis, possibly due to the limited number of studies reporting dyslipidemia prevalence across different baseline CD4+ T-cell count subgroups." (PMID 40585401, 2025). "We further found CD4+ memory cells expressing CD69 were most strongly associated with glucose intolerance and alterations in adipocyte gene expression, providing a plausible mechanistic link to altered mature adipocyte function and development of metabolic syndrome." (PMID 37711619, 2023). "Dyslipidemia was more common in PLWH residing in South China, with baseline CD4 cell count over 500 cells/μl or with a BMI ≥ 24 kg/m2." (PMID 40585401, 2025).
dyslipidemia (continued). "Patients with dyslipidemia exhibited significantly elevated counts of CD3+ T cells, CD4+ T cells, CD8+ T cells, and CD19+ B cells compared to healthy controls (p < 0.05)." (PMID 41377665, 2025). "The prevalence of dyslipidemia in ART-experienced PLWH exhibited significant variations across region, BMI group, baseline CD4 + T-cell count, and TCM therapy (p for comparison <0.05)." (PMID 40585401, 2025). "We also investigated the role of dyslipidemia in the observed changes in T-bet+Foxp3+ cell differentiation and IFN-γ production by memory CD4+ T cells of HDs and SLE patients." (PMID 33329581, 2020). "A blood test revealed dyslipidemia, hypothyroidism, increased plasma levels of the gonadotropins and positive HIV antibodies with a CD4+ cell count of 48/μL." (PMID 32149364, 2020). "Flow cytometry analysis showed that metabolic syndrome patients presented higher percentages of circulating CD3+, CD4+, and CD8+ lymphocytes than controls, and the percentage of CD8+ lymphocytes positively correlated with circulating glucose levels." (PMID 31109070, 2019). "A longer longitudinal study on a larger population that takes note of both viral loads and CD4 counts, together with the clinical and biochemical measures, will provide stronger evidence linking HIV and ART to dyslipidemia and coronary heart disease." (PMID 27051532, 2016). "In line with the active role of the AAT in the onset of NASH and of the metabolic syndrome, the AAT CD4+RORγt++ correlated with liver histology as well as with some features of metabolic impairment, including weight gain." (PMID 26229237, 2015). "The current study only focuses on CD3+ T cells, CD4+ T cells, and CD8+ T cells, and further studies are still needed to explore the role of more types of T and B immune cells in dyslipidemia and the complex relationship between bile acid metabolism and immune cells." (PMID 41377665, 2025). "Additionally, a higher percentage of CD3+CD4+ and CD3+CD8+ lymphocyte-platelet aggregates was found in the metabolic syndrome patients than in controls." (PMID 31109070, 2019). "In addition, those with a viral load ≥1000 copies/ml were 1.5-fold more likely to have dyslipidemia compared to those whose HIV-1 RNA was <1000 copies/ml, after adjusting for age, gender and CD4 cell count (aPR1.49; 95% CI: 1.14, 2.14; p = 0.02)." (PMID 28599673, 2017). "Baseline IMT was significantly associated with age (rho=0.497; p<0.001), basal glucemia (rho=0.323; p=0.001), triglycerides (rho=0.232; p=0.023), Framingham score (rho=0.324; p=0.001), CD4:CD8 ratio (rho=−0.176; p=0.05) and dyslipidemia (0.72±0.16 mm vs 0.63±0.11 mm; p=0.029)." (PMID 25397469, 2014). "Presence of metabolic syndrome, CIMT and baseline variables (fasting glucose, lipids, insulin, cardiovascular disease-related measurements, CD4+ T cell counts and HIV RNA levels, high-sensitivity C-reactive protein, serum sCD14, serum LPS) have previously been determined." (PMID 23510548, 2013). "In contrast, several mucosal/antiviral cytokines (e.g., IL-17 and IL-22) depend more directly on CD4+ T cell abundance and are relatively uncoupled from the metabolic status, indicating that dysglycemia and dyslipidemia do not uniformly affect all immune pathways." (PMID 41601726, 2026). "In addition to the prespecified factors of CD4 nadir, baseline HIV-RNA, and viral hepatitis status included in the model, region of care, dyslipidemia, and baseline BMI were the factors that remained statistically significantly associated with cLEE with P < .10, as outlined in the methods." (PMID 38919512, 2024). "Therefore, our results of increased levels of Tr1 cells and CD4+IL-10+ lymphocytes in T2DM are in agreement with previous reports regarding increased serum levels of IL-10 in patients with this condition as well as in prediabetic individuals and patients with metabolic syndrome." (PMID 38183564, 2024).
dyslipidemia (continued). "In treated patients the dyslipidemia correlates better with C-reactive protein and IL-6 levels, rather than with CD4 count or HIV viral load, suggesting that immune activation has a central role in the development of dyslipidemia." (PMID 30233499, 2018).
pulmonary fibrosis (99 papers, 2005 to 2026). Chronic progressive interstitial lung disorder characterized by the replacement of the lung tissue by connective tissue, leading to progressive dyspnea, respiratory failure, or right heart failure. "We conclude that CD4+ TRM cells are pathogenic drivers in pulmonary fibrosis, originating from circulating precursors and being regulated by Notch signaling, underscoring their relevance for therapeutic intervention." (PMID 41750395, 2026). "For example, balance between the CD4+T cell subsets has an essential impact on the development of lung fibrosis; Population data suggest that perivascular memory CD4+T cells play a pathogenic role in lethal COVID-19 pneumonia." (PMID 40433386, 2025). "The upregulation of programmed cell death-1 (PD-1) on CD4 T cells has been implicated in the production of inflammatory factors that contribute to lung fibrosis." (PMID 40483519, 2025). "For example, idiopathic pulmonary fibrosis is associated with increased expression of PD1+ on peripheral blood CD4+ T cells and within lung tissue and individuals with pulmonary fibrosis are at increased risk of developing lung cancer." (PMID 35359426, 2022). "CD103high Tregs can constrain lung fibrosis induced by CD103low tissue-resident pathogenic CD4+ T cells with higher production of effector cytokines, such as IL-4, IL-5, IL-13, IL-17A, and IFN-γ." (PMID 34488453, 2021). "Upon exposure to bleomycin, CD4+ T cells demonstrate significant production of IL-17A, a cytokine implicated in the pathogenesis and progression of pulmonary fibrosis." (PMID 25944985, 2015). "Chronic expression of ET-1 in the lungs of ET-1 transgenic mice causes progressive pulmonary fibrosis and recruitment of inflammatory cells, predominantly CD4-positive cells." (PMID 17687455, 2007). "In addition, in vivo, experiments in mice showed that CD103high Treg cells inhibited pulmonary fibrosis induced by CD103low tissue-resident pathogenic CD4+T cells." (PMID 40433386, 2025). "The strain-dependence in pulmonary CD4% was revealed to associate with extent of radiation-induced pulmonary fibrosis, and, we identified the lymphocyte profile in the lungs of untreated mice to correlate with the known strain responses to thoracic irradiation." (PMID 41261392, 2025). "CD4+ T cells in IPF: One of the main challenges in lung fibrosis is that the exact molecular and cellular mechanisms underlying the disease remain largely unknown." (PMID 37063828, 2023). "We hypothesized that loss of Th17 cells via CD4-specific deletion of mTORC1 activity would abrogate the development of bleomycin-induced pulmonary fibrosis." (PMID 27649073, 2016). "This study sought to define the contribution of CD4+ TRM cells to pulmonary fibrosis, their origin, and regulatory mechanisms." (PMID 41750395, 2026). "In our study, in the BLM-induced mouse model of pulmonary fibrosis, the dynamism of the CD4+ T cell population was observed to progress in parallel with interstitial collagen deposition." (PMID 41494735, 2026). "In BLM-induced mice, CD4+PD-1+ T cells in the lung tissues increased progressively, which was correlated with the severity of lung fibrosis." (PMID 41494735, 2026). "To further explore how CD4+PD-1+ T cells contribute to pulmonary fibrosis, we examined inflammatory cell infiltration and collagen deposition in mouse lungs at different time points after BLM induction." (PMID 41494735, 2026). "Current strategies for treating pulmonary fibrosis by targeting and regulating CD4+T cells and CD8+T cells." (PMID 40433386, 2025). "HU-308 (specifically binds to Cannabinoid receptor 2) attenuates lung fibrosis by inhibiting BLM-induced polarization of mouse Th2 cells through the specific activation of Cannabinoid Receptor 2 (CB2) on CD4+T cells." (PMID 40433386, 2025). "In patients with idiopathic pulmonary fibrosis (IPF), the expression of SEMA7A on CD4+CD25+FoxP3+ regulatory T cells (Tregs) is associated with disease progression." (PMID 40182927, 2025).
pulmonary fibrosis (continued). "CD4+T cells are a highly heterogeneous group of cells in the development of pulmonary fibrosis pathology." (PMID 40433386, 2025). "Guideline-discordant erlotinib rechallenge accelerated lymphocyte depletion, culminating in high-grade CMV viremia with CD4+ lymphocytopenia (0.16×109/L) and irreversible pulmonary fibrosis despite ganciclovir-induced virologic clearance." (PMID 41479888, 2025). "The administration of bortezomib alleviated bleomycin-induced pulmonary fibrosis, accompanied by reduced ratio of M2-polarized macrophages and decreased accumulation of CD4 T cells expressing CXCR6." (PMID 38789926, 2024). "Different studies have demonstrated that specific CD4+ T‐cell subsets are necessary to alleviate some interstitial lung damage or maintain IFN‐γ production, avoiding senescence‐associated pulmonary fibrosis." (PMID 39031504, 2024). "This is the first report of this finding, and it is in line with human models of lung fibrosis, where overexpression of CD4+PD1+ cells has been observed, suggesting dysregulation of immune checkpoint expression which influences the pathogenesis of IPF." (PMID 38540243, 2024). "Mechanistic experiments first recognized that PD-1+CD4+ T cells can promote pulmonary fibrosis and TGF-β production mainly through IL-17A, where T helper 17 (Th17) cells are the main CD4+ T cell subset expressing TGF-β." (PMID 38263193, 2024). "The retention and recruitment of CD4 T cells play a pivotal role in the exacerbation or remission of pulmonary fibrosis." (PMID 38789926, 2024). "For instance, CCL22 and CCL17, secretd by M2 macrophages, can recruit CCR4+CD4+ T helper 2 cells, thereby contributing to the pathophysiology of pulmonary fibrosis." (PMID 38789926, 2024). "In summary, our research revealed the increased secreation of CXCL16 from M2 macrophages in the context of bleomycin-induced pulmonary fibrosis, which was associated with the recruitment of CXCR6+ CD4 T cells." (PMID 38789926, 2024). "Specifically, phenotypes such as Activated & resting Treg %CD4+, CCR2-positive monocytes, and CD16-CD56 positive NK cells were associated with a reduced risk of pulmonary fibrosis." (PMID 38206731, 2023). "In the mouse model of bleomycin-induced pulmonary fibrosis, CD4 + CD25highFoxP3+ cells in the lung were increased after IL-2 complex treatment associated with aggravated lung fibrosis." (PMID 36979470, 2023). "Specifically, certain immune cells like activated & resting Treg %CD4+, CCR2 on monocytes, and CD4 on CD45RA + CD4 + were identified as protective factors against pulmonary fibrosis (beta < 0)." (PMID 38206731, 2023). "Sirolimus has been used therapeutically in CD4+ T cell–mediated fibrotic states, including idiopathic pulmonary fibrosis and renal interstitial fibrosis, making it a logical choice for testing as a potential therapeutic in LTS." (PMID 37159282, 2023). "To this end, we aimed to investigate the expression of PD-1/PD-L1 axis and CD4/CD8 ratio in the bleomycin model of pulmonary fibrosis." (PMID 37964265, 2023). "Upregulation of PD-1 in systemic CD4 + T cells promoted pulmonary fibrosis, while PD-L1 activation in fibroblasts of patients with IPF promoted invasion in vitro and lung fibrosis in vivo." (PMID 37964265, 2023). "We also assessed IL-17A and TGF-β1 production by sex, as CD4+ T cells promote pulmonary fibrosis through the STAT3-medicated production of IL-17A and TGF-β1." (PMID 36899902, 2023). "KDM6B expression, along with macrophages, CD3+ and CD4+ T cells, was significantly elevated in the lungs of bleomycin-induced pulmonary fibrosis mice compared to healthy controls." (PMID 37275887, 2023). "In the early stages of the fibrosis process, BLM increases the production of IL-17A in CD4+ T cells and γδT cells, which contributes to the development of lung fibrosis." (PMID 38132116, 2023).